OR51E1 (olfactory receptor family 51 subfamily E member 1)
Description:
Odorant receptor.
Synonyms: GPR164; OR51E1P; OR52A3P; POGR; PSGR2; GPR136; D-GPCR; DGPCR
Tractability: Small molecule: it belongs to a druggable protein family. Antibody: UniProt places it where antibodies can reach, with high confidence; its Gene Ontology location is reachable by antibodies, with high confidence; UniProt predicts a signal peptide or a membrane-spanning region.
Gene: Protein-coding gene on chromosome 11 (4,643,420 to 4,655,488, forward strand). Ensembl gene ENSG00000180785.
Subcellular location: Cell membrane
Pathways (Reactome):
Sensory Perception: Expression and translocation of olfactory receptors; Olfactory Signaling Pathway
Gene Ontology:
Molecular function: protein binding; olfactory receptor activity; G protein-coupled receptor activity; signaling receptor activity
Biological process: cellular response to lipid; detection of chemical stimulus involved in sensory perception of smell; G protein-coupled receptor signaling pathway; system process
Cellular component: plasma membrane; membrane
Genetic constraint (gnomAD): Loss-of-function variants: 13 observed, 15.33 expected, observed/expected ratio (o/e) 0.85, 90% interval 0.55 to 1.35. The upper end of that interval is the gene's LOEUF score, 1.35, which puts it in group 5 of 6, group 1 being the genes least tolerant of losing a copy. Missense variants: 391 observed, 422.07 expected, observed/expected ratio (o/e) 0.93, 90% interval 0.85 to 1.01. Synonymous variants: 166 observed, 162.71 expected, observed/expected ratio (o/e) 1.02, 90% interval 0.9 to 1.16.
Homologues: Orthologues: macaque OR51E1 (98% identical), mouse Or51e1 (93% identical), rabbit OR51E1 (93% identical), guinea pig OR51E1 (92% identical), rat Or51e1 (92% identical), pig OR51E1 (82% identical), tropical clawed frog or51ao2 (53% identical). Paralogues in human: OR51E2 (57% identical), OR51D1 (57% identical), OR51I2 (51% identical), OR51A4 (50% identical), OR51G2 (49% identical), OR52K2 (48% identical), OR51A2 (48% identical), OR52M1 (48% identical), OR52N5 (48% identical), OR52A5 (48% identical), OR52K1 (47% identical), OR52L1 (47% identical), and 39 more.
Diseases named in the same sentence as OR51E1 in open-access papers:
OR51E1 is named in the same sentence as 18 diseases in open-access papers, as found by Europe PMC text mining. Sharing a sentence is not in itself a finding about the gene and the disease. The quoted sentences say what the papers report.
prostate carcinoma (18 papers, 2012 to 2025). A carcinoma that arises from epithelial cells of the prostate gland. "In fact, OR51E2 and OR51E1 have been established as prostate specific G-coupled receptor PSGR and PSGR2 among prostate cancer cells and are associated with tumor progression, cancer cell invasiveness and metastasis." (PMID 31551495, 2019). "Analysis of a dataset from The Cancer Genome Atlas using GEPIA2 confirmed that OR51E2 and OR51E1 were significantly overexpressed in prostate cancer tissues, with OR51E2 being the more deregulated of the two." (PMID 40588561, 2025). "The activation of OR51E1 has been shown to suppress growth in human prostate cancer cells, therefore making it a possible alternative therapeutic target for prostate cancer." (PMID 39944883, 2025). "Relevant to our goal of olfactory diagnosis of prostate cancer, we note that homologs of human olfactory receptors OR51E1 and OR51E2 are overexpressed in human prostate cancer tumor tissue." (PMID 40445905, 2025). "For instance, OR2B6 overexpression has been reported in breast cancer, and OR51E1 has been found to be elevated in advanced prostate cancer and other solid tumors, consistent with our findings." (PMID 39769144, 2024). "There is also one report that the closely related receptor OR51E1 also inhibits growth of prostate cancer cells and another that OR10H1 plays a potential role in bladder cancer." (PMID 30542293, 2018). "OR51E2 is known to function as a biomarker for prostate cancer, and its paralog, OR51E1, was discovered as a potent biomarker for the small intestine and some types of lung cancer." (PMID 29497600, 2018). "OR51E2 and OR51E1 show an increased expression in prostate cancer cells, whereas OR51E1 is postulated to be a marker for lung cell carcinoids and cancer of the small intestine." (PMID 29497600, 2018). "Of note, one of the selected genes, OR51E1, has been proposed as a prostate cancer biomarker and formed part of the core enrichment in all three GSEA analyses." (PMID 25003216, 2014). "OR51E1 also has been reported to inhibit prostate cancer cell growth." (PMID 30542293, 2018). "Prostate cancer tissue served as a positive control for the detection of OR51E1 protein." (PMID 28116519, 2017). "OR51E1 was primarily identified in the prostate and is overexpressed in prostate cancer." (PMID 28116519, 2017). "In conclusion, OR51E1, OR51E2 or other olfactory receptors play an important role in the genesis, growth and treatment of prostate cancer cells, but their mechanisms need further study." (PMID 41347146, 2025). "OR51E1 expression seems to be retained in SI-NET and is found in other forms of neuroendocrine tumors as well as in prostate cancer that can display a neuroendocrine phenotype." (PMID 36959559, 2023). "OR51E1, a paralog of OR51E2, is also demonstrated to be functionally expressed in prostate cancer cells." (PMID 34452275, 2021). "We then selected six genes (HNRNPH1, DSC2, FBXO9, MANEA, OR51E1, PRR15L) for validation by qRT-PCR that were over-expressed in prostate cancer across all datasets and showed high fold changes in our microarray." (PMID 25003216, 2014). "Notably, OR51E1 (olfactory receptor E1 belonging to family 51) and OR51E2 (olfactory receptor E2 belonging to family 51) are known to be upregulated in prostate cancer tissues." (PMID 40588561, 2025). "Prostate cancer cell line experiments utilizing a previously validated OR51E1 agonist nonanoic acid and the structurally related non-agonist 1-nonanol, induced cellular senescence and thus decreased tumor proliferation." (PMID 36959559, 2023). "The OR51E1 agonist nonanoic acid treatment suppresses the proliferation of prostate cancer cells and triggers cellular senescence." (PMID 34452275, 2021).
prostate carcinoma (continued). "Indeed, OR51E2 and OR51E1 have been reclassified in human prostate cancer cells as prostate specific GPCRs (PSGR and PSGR2 respectively)." (PMID 31551495, 2019). "The second deorphanized OR is the 3-methyl-valeric acid and nonanoic acid receptor OR51E1, which was recently postulated as a marker for neuroendocrinic carcinoma cells and is overexpressed in human prostate cancer." (PMID 23405139, 2013).
lung carcinoids (6 papers, 2021 to 2025). "Likewise, the high expression of OR51E1 in somatostatin receptor-negative lung carcinoids and in small intestine neuroendocrine carcinomas makes OR51E1 a potential novel diagnostic biomarker in these types of tumor." (PMID 34204736, 2021). "OR51E1 for example has been suggested as target for diagnosis in somatostatin receptor-negative lung carcinoids, whereas OR3A4 promotes cisplatin resistance of non-small cell lung cancer." (PMID 33596996, 2021). "A previous study found that high levels of OR51E1 expression may be a biomarker for diagnosis and therapy in somatostatin receptor‐negative lung carcinoids." (PMID 40364562, 2025). "Furthermore, another group reported the high expression of OR51E1 in lung carcinoids, indicating that OR51E1 may play a role in somatostatin receptor-negative lung carcinoids." (PMID 34452275, 2021).
neuroendocrine carcinoma (3 papers, 2013 to 2023). A malignant neuroendocrine neoplasm composed of cells containing secretory granules that stain positive for NSE and chromogranin. "OR51E1 and OMP were strongly expressed in the SI-NET cell line GOT1 and in the SI-NEC (neuroendocrine carcinoma) cell line P-STS and weakly expressed in the breast cancer cell line MCF10A." (PMID 36959559, 2023).
colorectal cancer (2 papers, 2025). A primary or metastatic malignant neoplasm that affects the colon or rectum. "(2024) reported that butyrate derived from Roseburia intestinalis enhances the sensitivity of colorectal cancer to RT by activating the OR51E1/RALB axis and promoting autophagy." (PMID 40129929, 2025).
lung carcinoma (2 papers, 2018 to 2025). "Furthemore, ADGRE3 and OR51E1 expression was positively correlated with sensitivity to the drugs cisplatin, ribociclib, and pevonedistat, chemotherapeutics commonly used or being investigated in clinical trials for lung cancer." (PMID 40364562, 2025).
glioblastoma (1 paper, 2024). The most malignant astrocytic tumor (WHO grade IV). "The anatomical analysis using the Ivy Glioblastoma Atlas dataset further substantiated these findings, demonstrating significant OR51E1 up-regulation in regions of microvascular proliferation and hyperplastic blood vessels." (PMID 39769144, 2024).
heart failure (1 paper, 2023). Inability of the heart to pump blood at an adequate rate to meet tissue metabolic requirements. "OR51E1 and OR2B6 were used as examples of ORs expressed in cardiomyocytes that were respectively down-regulated and upregulated with heart failure." (PMID 37762009, 2023).
intestinal tumors (1 paper, 2023). "We then studied the long-term effects of nonanoic acid exposure, theoretically mirroring a continuous exposure to OR51E1 agonists in intestinal tumors, and found that this significantly decreased proliferation and altered cell morphology." (PMID 36959559, 2023). "Taken together, it is tempting to speculate that continuous exposure to OR51E1 agonists could drive intestinal tumors towards a more highly differentiated secretory phenotype with subsequent reduced proliferative activity." (PMID 36959559, 2023).
medullary thyroid cancer (1 paper, 2023). "Specifically, we found that OR51E2 and OR51E1 were expressed in thyroid cancer cell lines and human medullary thyroid cancer cells." (PMID 37371783, 2023).
rectal cancer (1 paper, 2025). A primary or metastatic malignant neoplasm that affects the rectum. "Mechanistically, the study suggests that Roseburia-intestinalis-derived butyrate enhances radiosensitivity through the activation of the OR51E1 G-protein-coupled receptor, which is overexpressed in rectal cancer." (PMID 40699664, 2025). "Butyrate’s activation of OR51E1 promotes radiogenic autophagy in CRC cells, which correlates with increased RALB expression in clinical rectal cancer tissues and CRC mouse models." (PMID 40699664, 2025).
small intestinal neuroendocrine neoplasms (1 paper, 2020). "For example, a high expression of OR51E1 has been found in small intestinal neuroendocrine neoplasms." (PMID 32512761, 2020).
tumor (12 papers, 2016 to 2025). "Considering the limited efficacy of current anti-angiogenic monotherapies in GBM and other solid tumors, OR51E1 presents a promising complementary therapeutic target for modulating tumor vasculature and potentially enhancing therapeutic outcomes." (PMID 39769144, 2024). "VEGFA, a key regulator of vascular remodeling and angiogenesis, was predominantly expressed in GBM neoplastic cells rather than vascular cells, suggesting potential paracrine signaling between VEGFA-secreting tumor cells and OR51E1-positive pericytes." (PMID 39769144, 2024). "The majority of OR51E1 protein located in the cytoplasm, while others in the perinuclear compartment of tumor cells." (PMID 31781505, 2019). "Consistently, OR51E1 expression was heterogeneously within benign prostatic as well as tumor samples and detectable in the cytoplasm and membrane." (PMID 27374083, 2016). "Additionally, OR51E1 has been found to act as a tumor biomarker for lung carcinoids (LC) in somatostatin receptor-negative tumor patients." (PMID 39944883, 2025). "This study explores the hypothesis that stimulating the chemosensing olfactory receptor 51E1 (OR51E1) decreases SI-NET proliferation suggesting a mechanism that explains a difference in proliferative rate based on tumor location." (PMID 36959559, 2023). "In both TCGA‐LUAD, in the GSE30219 and GSE18842 cohorts, the expression of ADRB1, ADGRD1, and ADGRE3 were reduced, whereas the expression of OR51E1 and LGR4 were elevated in tumor samples." (PMID 40364562, 2025). "Taken together, these results suggest that OR51E1 plays a crucial role in GBM vasculature, particularly in pericyte-mediated vascular remodeling and tumor angiogenesis, potentially influencing tumor progression and therapeutic resistance." (PMID 39769144, 2024). "For the second most highly expressed OR, OR51E1, we observed the highest FPKM value of 34.2 in benign prostatic and 39.7 in PCa tissue (P5)." (PMID 27374083, 2016). "Primary cultured tumor cells from 5 patients were utilized to determine the effect of OR51E1 agonist nonanoic acid on metabolic activity." (PMID 36959559, 2023). "Primary tumor cells from 5 SI-NET patients were treated for 72 h with 5 different concentrations of the OR51E1 agonist nonanoic acid, 1-nonanol (a structurally related non-agonist) and medium with vehicle (DMSO)." (PMID 36959559, 2023).
cancer (6 papers, 2018 to 2025). A tumor composed of atypical neoplastic, often pleomorphic cells that invade other tissues. "For instance, OR51E1 was highly expressed in stem cells of cancer, and it contributed to an increased risk score in our signature." (PMID 36186437, 2022). "In our study, we selected six human olfactory receptors including OR51E2, OR52cs, TAAR9, OR51E1, OR1A1, and OR1A2 that have been linked with research for the possible development of cancer treatment and detection methods." (PMID 39944883, 2025). "It is important to mention that OR2B6 unlike OR51E1 and OR51E2 lacks expression in healthy tissues, ensuring that the high expression does not come from an increase of a specific cell type but from the existence of the different transcript repertoire in cancer cells." (PMID 29497600, 2018).
OR51E1 also shares sentences with these, for which no sentence is quoted: breast carcinoma (2 papers); cancer of the small intestine (1); hypothyroidism (1); non-small cell lung carcinoma (1); thyroid cancer (1).